TNF (tumor necrosis factor)
Diseases named in the same sentence as TNF in open-access papers (continued):
Sharing a sentence is not in itself a finding about the gene and the disease.
pancreatic cancer (continued). "This gene set contains 219 genes that are up-regulated in BxPC3 pancreatic cancer cells after treatment with tumor necrosis factor (TNF)-, a pro-inflammatory cytokine." (PMID 23516507, 2013). "TNFα alone caused rapid and transient JNK activation in pancreatic cancer cells, as demonstrated by increased JNK phosphorylation." (PMID 24146961, 2013). "In this study, we provided evidence that digitoflavone sensitizes TNFα-induced apoptosis in human pancreatic cancer cells." (PMID 24146961, 2013). "Pancreatic cancer cell-conditioned medium promoted mast cell migration and co-culture of mast cells with pancreatic cancer cells or PSCs stimulated mast cell activation, confirmed by the release of tryptase and tumor necrosis factor-α." (PMID 24198790, 2013). "Endostatin is expressed differently in variable pancreatic cancer cell lines, which is modulated by TNF-α-dependent elastase." (PMID 23426020, 2013). "We found that pretreatment with digitoflavone, a plant flavonoid, greatly sensitized TNFα-induced apoptotic cell death in several human pancreatic cancer cells." (PMID 24146961, 2013). "Tsutom has reported that intratumoral injection of recombinant human TNFα inoperable cases of pancreatic cancer brought about regression of the tumor or a decrease in tumor markers." (PMID 24146961, 2013). "Most human pancreatic cancer cells are resistant to tumor necrosis factor (TNF)-related apoptosis-inducing ligand (TRAIL)-mediated apoptosis." (PMID 24204567, 2013). "Digitoflavone significantly sensitized TNFα-induced apoptosis in a number of human pancreatic cancer cell lines, an effect which was discovered for the first time by this study." (PMID 24146961, 2013). "We assessed the effects of TNF and its two receptors on the progression of pancreatic cancer by in vivo bioluminescence imaging in a syngeneic orthotopic tumor mouse model with Panc02 cells." (PMID 24098720, 2013). "TNFα increased Claudin 1 expression in human pancreatic cancer cells, and in airway smooth muscle cells." (PMID 22675434, 2012). "Here, we aimed at deciphering how MSLN overexpression in pancreatic cancer cells affects sensitivity to TNF-α-induced apoptosis." (PMID 21880146, 2011). "In this study we have utilized this mouse model to report on the non-invasive detection of pancreatic tumor growth in response to the TNF-alpha inhibitor Infliximab." (PMID 21699694, 2011). "TNF-α was found to support pancreatic cancer cell growth through epidermal growth factor receptor (EGFR) and transforming growth factor (TGF-α) expression." (PMID 21880146, 2011). "Our study demonstrated that both LPS and TNF-α can upregulate it and increase the invasiveness of pancreatic cancer cells." (PMID 21760774, 2011). "Third, their expression was increased by pancreatic cancer cells due to exogenous TNF-α and LPS but the elevated expression of MMP-9 was inhibited by COX-2 inhibitor NS398 and was elevated again when treated with exogenous PGE2." (PMID 21760774, 2011). "A similar interaction between TNF-α, NF-κB and EMT was demonstrated in pancreatic cancer cells, with transfection with a dominant negative form of IκBα abrogating TNF-α-induced EMT." (PMID 24281219, 2010). "Treatment of MA inhibited TNFα induced p65 nuclear translocation and p65 phosphorylation (right), suggesting that MA suppresses TNFα induced NF-κB nuclear translocation and activation in pancreatic cancer cells." (PMID 20367887, 2010). "And finally, we demonstrated that the expression levels of NF-κB-mediated downstream genes, including anti-apoptosis genes, proliferation genes, and metastasis related genes induced by TNFα, were all inhibited by MA in the pancreatic cancer cells." (PMID 20367887, 2010). "Our data indicated that MA together with TNFα potentiated cell apoptosis from 6.0 ± 2.01% to 51 ± 5.32% in pancreatic cancer cells (top)." (PMID 20367887, 2010).
pancreatic cancer (continued). "Previous studies have shown that the secretion of TNFα was highly increased in pancreatic tumor tissues and even in serum in vivo." (PMID 20367887, 2010). "When used together, MA and TNFα synergistically induced cell death to 56 ± 5.34% in Panc-28 cells, indicating that MA can significantly decrease pancreatic cancer cell viability induced by TNFα in vitro." (PMID 20367887, 2010). "In this study, we demonstrated that MA greatly potentiated the inhibitory effect of TNFα on the growth of pancreatic cancer through activation of apoptosis." (PMID 20367887, 2010). "To determine the effects of MA on pancreatic cancer cell invasion, we performed the transwell invasion assay and found that MA can markedly inhibit TNFα-induced Panc-28 pancreatic cancer cell invasion, while MA alone had no significantly inhibitory activity." (PMID 20367887, 2010). "In pancreatic cancer patients indeed increased levels of several cytokines such as IL-6, IL-18 and TNF-alpha can be found." (PMID 20961421, 2010). "In various pancreatic cancer cell lines, MA or TNFα alone moderately inhibited cancer cell growth and induced apoptosis." (PMID 20367887, 2010). "The strong inhibitory effects of MA on TNFα-induced NF-κB DNA binding activity were further confirmed in three more different type pancreatic cancer cell lines Panc-1, BXPC-3 and ASPC-1." (PMID 20367887, 2010). "Our data demonstrate that MA can potentiate the anti-tumor activities of TNFα and inhibit pancreatic tumor growth and invasion by activating caspase-dependent apoptotic pathway and by suppressing NF-κB activation and its downstream gene expression." (PMID 20367887, 2010). "Together, all of our results suggested that MA strongly inhibited TNFα-induced NF-κB activity in pancreatic cancer cells." (PMID 20367887, 2010). "In the current study, we found that MA or TNFα alone showed moderate apoptosis activities in pancreatic cancer cell lines." (PMID 20367887, 2010). "In conclusion, we demonstrated that an anti-CEA/anti-TNFα BAb can markedly enhance the radioresponse of pancreatic tumour xenografts in nude mice." (PMID 14612914, 2003). "To overcome these limitations, we used a BAb directed against CEA and human TNFα to target this cytokine to the human pancreatic carcinoma cells BxPC-3 treated simultaneously with RT." (PMID 14612914, 2003). "The aim of this study was to treat carcinoembryonic antigen (CEA)-expressing pancreatic carcinoma cells with tumour necrosis factor alpha (TNFα) and simultaneous radiation therapy (RT), using a bispecific antibody (BAb) anti-TNFα/anti-CEA." (PMID 14612914, 2003). "In addition, the KEGG analysis significantly enriched multiple pathways that have been reported to be closely related to pancreatic cancer development such as the TNF signaling pathway and AGE-RAGE signaling pathway." (PMID 41391757, 2025). "These inflammatory factors, such as TNF-α and IL-6, can upregulate the expression of matrix metalloproteinases (MMPs), degrading the extracellular matrix and promoting the invasion and metastasis of pancreatic cancer cells." (PMID 40430234, 2025). "More broadly, our study highlights a critical facet of the tumor-TAM interaction: while proinflammatory cytokines IL-1β and TNF-α promote tumor progression, they also create a metabolic vulnerability in pancreatic cancer cells by enforcing reliance on the de novo pyrimidine synthesis pathway." (PMID 41243973, 2025). "Importantly, the Cad-mediated suppression of pancreatic cancer was dependent on TAMs and cytokines IL-1 and TNF-α." (PMID 41243973, 2025). "Furthermore, supernatants from pancreatic cancer cells treated with TNF-α significantly promoted tube formation, whereas those treated with CalebinA significantly suppressed it." (PMID 40871669, 2025). "Additionally, TNF‐α selectively inhibits the gene expression of albumin, playing a critical role in the development of malnutrition in pancreatic cancer." (PMID 40631494, 2025).
pancreatic cancer (continued). "Vectored delivery of TNFα culminated in TNFerade, a replication incompetent adenoviral vector, which was studied in a randomized phase 3 trial in combination with fluorouracil and radiotherapy, for the treatment of locally advanced pancreatic cancer." (PMID 38546220, 2024). "However, in the pancreatic cancer microenvironment, TNF-α binds to TNF-R2, leading to upregulation of the EGFR and subsequent cancer cell proliferation." (PMID 39195299, 2024). "Similarly, treatment with EGFR inhibitor targeted therapy suppresses MDSCs and Arg1 expression, resulting in heightened levels of Th1 cytokines such as IL-12 and tumor necrosis factor-alpha (TNF-α) and reduced pancreatic cancer." (PMID 38464388, 2024). "Moreover, TNFα secreted from the infiltrating macrophages enhanced PD-L1 expression by activating NF-κB, resulting in a poor prognosis in pancreatic cancer." (PMID 38166970, 2024). "In line with this, we previously showed that pancreatic tumor organoids from cachectic and non-cachectic pancreatic cancer patients expressed variable levels of known cachexia-associated cytokines, including IL-6, TNF-α, IL-8, IL-1α, IL-1β, Mcp-1, and LIF." (PMID 38339292, 2024). "Several studies have explored targeting TNF-α for pancreatic cancer treatment." (PMID 39195299, 2024). "The inflammatory cytokines TNF and IL-1α are also known to promote pancreatic cancer." (PMID 37814340, 2023). "In this study, TNF was also underexpressed in pancreatic cancer cells." (PMID 37893166, 2023). "Studies have shown that, in pancreatic cancer models, ω6-PUFAs have antitumor activity and inhibit the continuous growth of pancreatic tumors, ω6-PUFAs inhibits the proliferation of prostate cancer cells and regulates inflammatory IL-6 and TNF by affecting the production of cytokines-α." (PMID 35743814, 2022). "Overall, the variety of gene mutations and the combination of the upregulation of growth factors, such as interleukins 8, 6, and 1, vascular endothelial growth factor (VEGF), as well as Tumor necrosis factor (TNF), make pancreatic cancer remarkably unsusceptible to treatment." (PMID 35743107, 2022). "Second, although we have provided evidence that VRK2 activates TNFα/NF-kB signaling in pancreatic cancer cells, when or under what conditions VRK2 controls NF-kB signaling regulation remains largely unknown." (PMID 35173553, 2022). "We found that overexpression of VRK2 in pancreatic cancer cells could activate TNFα/NF-kB pathway, leading to a shift from apoptosis to survival in the circumstance of TNFα." (PMID 35173553, 2022). "And then, we co-cultured TNFSF9-knockdown pancreatic cancer cells with U937-derived macrophages and found that compared with the sh-NC group, the mRNA levels of M1-type markers (TNF-α and IL-8) in sh-TNFSF9-1 and sh -TNFSF9-2 groups were increased and the mRNA levels of IL-1β were decreased." (PMID 34517345, 2021). "Importantly, these results indicate that TNF-α induces an increase in CAFs also in vivo in murine pancreatic tumours." (PMID 34172716, 2021). "In addition, a recent study demonstrates that activated macrophage-derived TNF-α can upregulate PD-L1 expression in pancreatic cancer cells, which leads to poor prognosis." (PMID 34276760, 2021). "We examined whether TNF-α induces the formation of CAFs and fibrosis in pancreatic tumours and thereby whether TNF-α may be responsible for the strong desmoplastic reaction characteristic of PDAC." (PMID 34172716, 2021). "Also, luteolin treatment and knockdown of miR-301-3p sensitized pancreatic cancer cells to the tumor necrosis factor (TNF)-related apoptosis-inducing ligand (TRAIL)." (PMID 34295245, 2021).
pancreatic cancer (continued). "Beyond the direct activity of adipose tissue-derived TNF-α in cancer cells, the pivotal role of this cytokine in supporting adipose tissue inflammation might be even more relevant on pancreatic tumor development and progression." (PMID 32659999, 2020). "Apigenin treatment decreased cell survival and increased apoptosis of AsPC-1, PANC-1 and MiaPaCa-2 pancreatic cancer cell lines through the inhibition of tumor necrosis factor-alpha (TNFα)-induced DNA binding (p65 and p50 subunits), resulting in reduced transcriptional activities of NF-kB." (PMID 32717779, 2020). "Moreover, TNF-α affects tumor cell growth and invasion in pancreatic tumor both in vitro and in vivo." (PMID 31191652, 2019). "In a mouse model of pancreatic cancer, TNFα induces the activation of Ikkβ, a component of the NF-κB signaling, that promotes the expression of Notch target genes HES1 by inducing histone H3 phosphorylation at the HES1 promoter resulting in transcriptional activation." (PMID 30154786, 2018). "Conversely, pancreatic cancer cell-derived conditioned media and the individual cytokines, TNF-α and TGF-β induced the expression of S100A8 and S100A9 proteins in the HL-60 monocytic cell line and primary human monocytes, while FGF and IL-8 induced the expression of S100A9 only." (PMID 30558665, 2018). "A number of circulating pro-inflammatory cytokines have been implicated in pancreatic cancer cachexia including interleukin 6 (IL-6), interleukin 8 (IL-8), transforming growth factor beta (TGF-β), tumor necrosis factor alpha (TNFα), and monocyte chemoattractant protein-1 (MCP-1)." (PMID 30513792, 2018). "TNF-α concentration was increased in the cholangiocellular carcinoma and pancreatic cancer groups." (PMID 29410961, 2017). "We believe that the inhibition of TNFα could additionally assist chemotherapeutic strategies in pancreatic cancer, possibly by inhibiting immunosuppressive macrophages." (PMID 28160574, 2017). "To evaluate whether the effect of vagotomy was related to TNFα in pancreatic cancer we analyzed the survival in tumor bearing TNFα −/− mice." (PMID 28160574, 2017). "Additionally, there are several reports emphasizing the detrimental functions of TNFα in pancreatic cancer." (PMID 28160574, 2017). "Especially treatment options focusing on tumor infiltrating macrophages and anti-TNFα-pathways could help to improve the prognosis of pancreatic cancer." (PMID 28160574, 2017). "Additionally, NF-κB pathway inhibitor sodium salicylate inhibits phosphorylation and degradation of NF-κB negative regulator IκBα and subsequently enhances TNF-α induced apoptosis in BxPC-3 human pancreatic cancer cells." (PMID 28288630, 2017). "Employing TNFα −/− mice we could show that the effects of sub-diaphragmatic vagotomy in pancreas cancer were dependent on TNFα." (PMID 28160574, 2017). "It is well accepted that TNF-α induces pancreatic cancer cell proliferation." (PMID 28578701, 2017). "A preclinical study showed that anti-TNF antibody inhibits pancreatic tumor growth and metastasis." (PMID 29069789, 2017). "IL-6 and IL-10 were significantly increased in both the HCC and GBC groups, whereas IL-2, IL-6, IL-10, and TNF-α were significantly increased in the cholangiocellular carcinoma group, and IL-2, IL-6, IL-8, and TNF-α were significantly increased in the pancreatic cancer group." (PMID 29410961, 2017). "In addition, it was shown that expression of the TNF-α gene was upregulated in patients with pancreatic cancer and normalized after the tumor was surgically resected." (PMID 26856534, 2016). "Furthermore, we investigated the prognostic value of TNF-α expression in all pancreatic cancer cases and PDAC cases." (PMID 27835602, 2016).
pancreatic cancer (continued). "Our observations demonstrate that activation of PPARβ/δ by a specific agonist reduces the TNFα-induced mRNA levels of genes known to be involved in the regulation of human pancreatic cancer cell invasion and metastasis, and this negative regulation is also manifested at the protein level." (PMID 23737761, 2013). "The aim of this study was to investigate the effect of SmacN7 on the biological characteristics of pancreatic cancer cell lines, and to assess the effect of SmacN7 on the sensitivity to tumor necrosis factor (TNF)-related apoptosis-inducing ligand (TRAIL) and gemcitabine." (PMID 23833637, 2013). "The role of TNF in pancreatic tumor progression is controversial." (PMID 24098720, 2013). "In pancreatic cancer TNF plays a complex yet until now poorly understood role." (PMID 24098720, 2013). "Monocyte chemotactic protein-1 is produced by pancreatic cancer cells in response to TNFα challenge and may contribute to the accumulation of tumor-associated macrophages which influence key events in the tumor invasion process." (PMID 23737761, 2013). "To help find additional factors which might affect the therapy, we examined the resistance of MSLN-overexpressing pancreatic cancer cell lines to TNF-α-induced growth inhibition/apoptosis." (PMID 21880146, 2011). "TNF-α also plays a significant role in the inflammatory etiology of pancreatic cancer." (PMID 21880146, 2011). "Several evidences found that TNFα could induce pancreatic cancer cell apoptosis in vitro and in vivo." (PMID 20367887, 2010). "TNFα-induced IκBα degradation happens within 10 minutes of stimulation and reached a maximum at 20 minutes, but treatment of MA significantly inhibited TNFα induced IκBα degradation in pancreatic cancer cells." (PMID 20367887, 2010). "However, MA dramatically increased cell apoptosis and inhibited NF-κB activity induced by TNFα in various pancreatic cancer cell lines, suggesting a synergistic effect of MA together with TNFα." (PMID 20367887, 2010). "The aim of this study was to determine whether MA, a nontoxic microchemical ingredient and widely present in the diet, could sensitize pancreatic cancer to the treatment of TNFα." (PMID 20367887, 2010). "To determine the effects of MA, a recently discovered triterpenoid isolated as the main compound from olive-skin pomace on pancreatic cancer cell growth, we treated Panc-28 pancreatic cancer cells with different concentration of TNFα, MA or together and then measured cell proliferation by MTS assay." (PMID 20367887, 2010). "Similar effects were also observed in 2 other pancreatic cancer cell lines, AsPC-1 and BxPC-3, suggesting that MA is an effective agent in suppressing pancreatic cancer cell proliferation in the presence of TNFα." (PMID 20367887, 2010). "Many studies also showed that tumor secreted-TNFα could prevent pancreatic cancer cell from apoptosis mediated by exogenous TNFα by activating NF-κB signaling pathway." (PMID 20367887, 2010). "Previous studies indicate that TNFα have multiple roles in pancreatic cancer." (PMID 20367887, 2010). "To confirm the synergistic effect of MA and TNFα on cell apoptosis, we examined wheather MA affects TNFα-induced activation of caspase apoptotic pathway in pancreatic cancer cells by measuring the marker proteins, PARP and caspase-3, using Western blot analysis." (PMID 20367887, 2010). "In this study, we demonstrate that MA significantly enhanced TNFα-induced inhibition of pancreatic cancer cell proliferation, invasion, and potentiated TNFα-induced cell apoptosis by suppressing TNFα-induced NF-κB activation in a dose- and time-dependent manner." (PMID 20367887, 2010). "In summary, our data demonstrate that MA can potentiate the anti-tumor activity of TNFα, inhibit pancreatic cancer proliferation, invasion, and induce tumor cell apoptosis by increasing caspase-mediated apoptotic activation and suppressing NF-κB activity in pancreatic tumors." (PMID 20367887, 2010).